PAH (phenylalanine hydroxylase)
Description:
Catalyzes the hydroxylation of L-phenylalanine to L-tyrosine.
Synonyms: PH; PKU; PKU1
Tractability: Small molecule: an approved drug acts on it; a structure with a bound ligand is known; it has a high-quality binding pocket; it belongs to a druggable protein family. PROTAC: its protein half-life has been measured; a small molecule that binds it is known.
Target class: Enzyme; Oxidoreductase
Gene: Protein-coding gene on chromosome 12 (102,836,889 to 102,958,410, reverse strand). Ensembl gene ENSG00000171759.
Subcellular location (Human Protein Atlas): Endoplasmic reticulum; Vesicles
Pathways (Reactome):
Disease: Phenylketonuria
Metabolism: Phenylalanine metabolism
Gene Ontology:
Molecular function: phenylalanine 4-monooxygenase activity; iron ion binding; monooxygenase activity; oxidoreductase activity, acting on paired donors, with incorporation or reduction of molecular oxygen, reduced pteridine as one donor, and incorporation of one atom of oxygen
Biological process: amino acid biosynthetic process; catecholamine biosynthetic process; L-phenylalanine catabolic process; L-tyrosine biosynthetic process; aromatic amino acid metabolic process
Cellular component: cytosol
Genetic constraint (gnomAD): Loss-of-function variants: 56 observed, 55.3 expected, observed/expected ratio (o/e) 1.01, 90% interval 0.82 to 1.26. The upper end of that interval is the gene's LOEUF score, 1.26, which puts it in group 5 of 6, group 1 being the genes least tolerant of losing a copy. Missense variants: 553 observed, 552.98 expected, observed/expected ratio (o/e) 1, 90% interval 0.93 to 1.07. Synonymous variants: 192 observed, 203.5 expected, observed/expected ratio (o/e) 0.94, 90% interval 0.84 to 1.06.
Gene-disease validity (ClinGen):
ClinGen rates the evidence that PAH causes each of these diseases.
phenylketonuria (autosomal recessive): Definitive. Phenylketonuria (PKU) is the most common inborn error of amino acid metabolism and is characterized by mild to severe mental disability in untreated patients.
Homologues: Orthologues: chimpanzee PAH (99% identical), dog PAH (95% identical), rabbit PAH (94% identical), mouse Pah (92% identical), pig PAH (92% identical), guinea pig PAH (91% identical), rat Pah (90% identical), macaque PAH (88% identical), zebrafish pah (74% identical), Drosophila melanogaster Hn (61% identical), Caenorhabditis elegans pah-1 (56% identical). Paralogues in human: TPH2 (54% identical), TPH1 (53% identical), TH (50% identical).
Diseases named in the same sentence as PAH in open-access papers:
PAH is named in the same sentence as 70 diseases in open-access papers, as found by Europe PMC text mining. Sharing a sentence is not in itself a finding about the gene and the disease. The quoted sentences say what the papers report.
phenylketonuria (391 papers, 2009 to 2026). "Phenylketonuria (OMIM#261600) is an autosomal recessive metabolic disorder characterized by a deficiency in the enzyme PAH, leading to the accumulation of Phe and subsequent neurological complications." (PMID 41346395, 2026). "Phenylketonuria (PKU) is an autosomal recessive disorder caused by a deficiency of phenylalanine hydroxylase (PAH), leading to the accumulation of phenylalanine (Phe) and an increased risk of developmental disorders." (PMID 41346395, 2026). "From a genetic perspective, Phenylketonuria is an inborn defect of phenylalanine metabolism due to pathogenic variants in the PAH gene." (PMID 41158521, 2025). "Phenylketonuria is a genetic condition caused by a defect in gene that helps produce the phenylalanine hydroxylase enzyme required for the breakdown of phenylalanine that results in rising levels of phenylalanine in blood and tissues." (PMID 39920746, 2025). "Phenylketonuria (PKU) is an inherited disorder caused by mutations in the phenylalanine hydroxylase (PAH) gene that result in the amino acid phenylalanine (Phe) building up in the blood." (PMID 40943640, 2025). "Phenylketonuria (PKU) is an autosomal recessive metabolic disorder characterized as deficiencies in phenylalanine hydroxylase, leading to neurotoxic effects and neurodevelopmental challenges." (PMID 40042669, 2025). "Phenylketonuria (PKU) is a prevalent inborn error in phenylalanine (Phe) metabolism caused by a deficiency in phenylalanine hydroxylase (PAH)." (PMID 40730740, 2025). "Phenylketonuria is a metabolic disorder caused by a deficiency of the hepatic enzyme PAH, resulting in high levels of the AA phenylalanine in the blood and brain." (PMID 41158521, 2025). "PAH gene, associated with phenylalanine hydroxylase deficiency, was observed with a frequency of 1:27." (PMID 41303398, 2025). "Phenylketonuria is an unusual inherited metabolic disease induced by mutations of the phenylalanine hydroxylase gene, resulting in phenylalanine accumulation." (PMID 41158521, 2025). "Phenylketonuria is an autosomal recessive disorder characterized by the deficiency of phenylalanine hydroxylase, which converts phenylalanine into tyrosine." (PMID 40751258, 2025). "Phenylalanine hydroxylase deficiency (PAHD) is caused by mutations in the PAH gene resulting in reduction or loss of PAH enzyme activity, and lead to high concentrations of phenylalanine in blood and cerebrospinal fluid." (PMID 41291872, 2025). "Phenylketonuria, otherwise known as a deficiency of phenylalanine hydroxylase (PAH), is an autosomal recessive genetic disorder." (PMID 41158521, 2025). "Phenylketonuria (PKU) is an inherited metabolic disorder caused by mutations in the phenylalanine hydroxylase (PAH) gene, leading to phenylalanine accumulation and clinical symptoms such as intellectual disability and hypopigmentation." (PMID 41274966, 2025). "Pahenu2 (BTBR-Pahenu2/J) mice carry a T835C missense mutation, yielding an F263S single amino acid substitution that causes severely diminished PAH catalytic activity in homozygotes and provide a model of severe phenylketonuria." (PMID 40351478, 2025). "Phenylketonuria (PKU) is the most common inborn disorder of amino acid metabolism caused by biallelic pathogenic variants in phenylalanine hydroxylase (PAH) gene." (PMID 40473815, 2025). "Phenylketonuria (PKU) is an autosomal recessive inherited metabolic disorder caused by a deficiency of the enzyme phenylalanine hydroxylase, responsible for the conversion of phenylalanine into tyrosine." (PMID 41141261, 2025). "Phenylketonuria (PKU) is a hereditary metabolic disorder caused by mutations in the phenylalanine hydroxylase (PAH) gene, leading to the accumulation of phenylalanine (Phe) in the blood." (PMID 40496820, 2025). "Phenylketonuria (PKU) is a monogenic disorder caused by pathogenic variants in the gene encoding phenylalanine hydroxylase (PAH), an enzyme essential for phenylalanine (Phe) metabolism." (PMID 40806304, 2025).
phenylketonuria (continued). "Phenylketonuria (PKU) is an autosomal recessive inherited metabolic disorder caused by mutations in the phenylalanine hydroxylase (PAH) gene, leading to PAH enzyme deficiency." (PMID 41274966, 2025). "Phenylketonuria, the most common inherited metabolic disease, results from a deficiency of phenylalanine hydroxylase enzyme activity that causes high blood phenylalanine levels." (PMID 39364650, 2024). "Phenylketonuria (PKU) is caused by mutations in the phenylalanine hydroxylase (PAH) gene, leading to the accumulation of phenylalanine in the body." (PMID 39707395, 2024). "Phenylketonuria (PKU) is an autosomal recessive innate error of metabolism due to a deficiency in the enzyme phenylalanine hydroxylase, produced in the liver." (PMID 38988862, 2024). "This spectrum includes classical phenylketonuria (PKU) caused by a deficiency in phenylalanine-4-hydroxylase (PAH), resulting from mutations in the PAH gene." (PMID 38731816, 2024). "Phenylketonuria (PKU) is an inborn error of amino acid metabolism caused by mutations in the phenylalanine hydroxylase gene (PAH)." (PMID 38791104, 2024). "Phenylketonuria (PKU [MIM: 261600]) is a disorder of phenylalanine (Phe) metabolism wherein deficiency of phenylalanine hydroxylase (PAH) results in elevated blood Phe levels." (PMID 37922902, 2024). "Phenylketonuria (PKU) is a rare inborn error of metabolism disease caused by reduced functionality of phenylalanine hydroxylase (PAH), an essential enzyme converting phenylalanine (Phe) to tyrosine." (PMID 39598323, 2024). "Background/Objectives: Phenylketonuria is a hereditary metabolic disorder characterized by a deficiency of phenylalanine hydroxylase." (PMID 39408322, 2024). "Phenylketonuria (PKU) is a rare genetic disorder caused by a deficiency in the activity of the enzyme phenylalanine hydroxylase (PAH), the enzyme responsible for converting phenylalanine (Phe) into tyrosine (Tyr)." (PMID 39408315, 2024). "Phenylketonuria (PKU) is an autosomal recessive inborn error of metabolism resulting from a deficiency of phenylalanine hydroxylase (PAH)." (PMID 37701331, 2023). "Phenylketonuria (PKU) is a metabolic genetic disorder that causes a defect in phenylalanine hydroxylase, preventing the conversion of phenylalanine to tyrosine and increasing blood phenylalanine levels." (PMID 36671972, 2023). "Phenylketonuria (PKU) is an autosomal recessive inherited disorder of phenylalanine metabolism caused by pathological variants in the phenylalanine hydroxylase (PAH) gene, which results in a deficiency of phenylalanine hydroxylase (PAH)." (PMID 37571317, 2023). "Further, we explore the function of PAH (a key metabolic enzyme associated with Phenylketonuria), the gene exhibiting the highest prevalence of pathogenic variants in a pan-cancer (1.8%) compared to controls (0.6%)." (PMID 38143269, 2023). "Schwank and colleagues observed a 10% base editing rate of phenylalanine hydroxylase mutations in the liver of mice with phenylketonuria model by delivery of LNP encapsulating SaCas9-BE3 mRNA." (PMID 37027099, 2023). "The PAH P281L variant is one of the most common variants identified in phenylketonuria (PKU) patients." (PMID 37301931, 2023). "Phenylketonuria (PKU) is an autosomal recessive disease resulting from a deficiency of the enzyme phenylalanine hydroxylase (PAH)." (PMID 37421234, 2023). "Our research focuses on genotypes based on PAH gene mutations for phenotype prediction in phenylketonuria." (PMID 37004080, 2023). "Osteopenia is observed in some patients affected by phenylalanine hydroxylase-deficient phenylketonuria." (PMID 35820909, 2022). "Some genetic mutations in the PAH gene lead to destabilization of the PAH enzyme, leading to phenylketonuria (PKU)." (PMID 35987969, 2022). "Eleven of these are in the PAH gene (126 ancient samples in total), a gene associated with the condition phenylketonuria in modern populations." (PMID 35749392, 2022).
phenylketonuria (continued). "Phenylketonuria (PKU) is an inborn error of metabolism caused by a deficiency of the enzyme phenylalanine hydroxylase (PAH) which results in elevated levels of phenylalanine (Phe) and reduced levels of tyrosine." (PMID 35907851, 2022). "Eleven of these are in the PAH gene (125 ancient samples in total), a gene associated with the condition phenylketonuria in modern populations." (PMID 35749392, 2022). "Osteopenia is an under‐investigated clinical presentation of phenylalanine hydroxylase (PAH)‐deficient phenylketonuria (PKU)." (PMID 36101821, 2022). "Phenylketonuria (PKU) is an inborn error of metabolism caused by a deficiency in functional phenylalanine hydroxylase (PAH), resulting in accumulation of phenylalanine (Phe) in patients’ blood and organs." (PMID 36277393, 2022). "For gene–environment interactions, phenylketonuria only occurs when phenylalanine hydroxylase mutations are present and phenylalanine-containing foods are consumed simultaneously." (PMID 35452412, 2022). "Phenylketonuria (PKU) is an autosomal recessive inborn error of metabolism caused by a deficiency of the hepatic enzyme phenylalanine hydroxylase (PAH)." (PMID 36277393, 2022). "Regarding phenylketonuria, 152 (4.66%) pregnant women carried disease‐associated variants in the PAH gene." (PMID 35502621, 2022). "Phenylketonuria (PKU) is a rare autosomal recessive inborn error of metabolism where a phenylalanine hydroxylase (PAH) deficiency leads to the accumulation of amino acid phenylalanine (Phe) in the blood and brain." (PMID 35216344, 2022). "Phenylketonuria (PKU) is an inborn disease caused by mutations in the phenylalanine hydroxylase (PHA) gene." (PMID 34502086, 2021). "The impairment of the hepatic enzyme phenylalanine hydroxylase (PAH) causes elevation of phenylalanine levels in blood and other body fluids resulting in the most common inborn error of amino acid metabolism (phenylketonuria)." (PMID 33465300, 2021). "Phenylketonuria (PKU) is a congenital recessive disease caused by changes to the gene encoding PAH (phenylalanine hydroxylase." (PMID 34200310, 2021). "In phenylketonuria, a human congenital disorder in which a mutation in phenylalanine hydroxylase leads to high phenylalanine concentrations, a deficit of tyrosine and catecholamines is observed." (PMID 34551799, 2021). "Phenylketonuria (PKU) is caused by autosomal recessive variants in phenylalanine hydroxylase (PAH) and can lead to neurotoxicity." (PMID 33824313, 2021). "Phenylketonuria (PKU) is a rare inherited metabolic disorder caused by defects in the phenylalanine-hydroxylase gene (PAH), the enzyme catalyzing the conversion of phenylalanine to tyrosine." (PMID 34784942, 2021). "Phenylketonuria is an autosomal recessive disorder caused by defects in the PAH gene, occurring in 1:10,000 live births in Europe, with higher prevalence in some countries, including Italy." (PMID 34784942, 2021). "PAH (phenylalanine hydroxylase, an enzyme which catalyzes the conversion of phenylalanine to tyrosine) has been associated with phenylketonuria, an autosomal recessive metabolic disorder." (PMID 34830779, 2021). "In the second test case, we compare results for compounds associated with Phenylketonurias, a group of metabolic diseases induced by a defect in the production of phenylalanine hydroxylase." (PMID 34478489, 2021). "Phenylketonuria (PKU) is an autosomal recessive inherited disorder characterised by a deficiency in phenylalanine hydroxylase (PAH) associated with a wide range of cognitive and psychiatric sequelae." (PMID 33461585, 2021). "Classic phenylketonuria occurs due to mutations in the q22–24 region of chromosome 12, which affects the structure and function of phenylalanine hydroxylase." (PMID 33805682, 2021).
phenylketonuria (continued). "Some hotspot mutations were observed for several IEMs, including PAH gene c.728G>A for phenylketonuria; MMACHC gene c.609G>A and c.567dupT, MMUT gene c.323G>A for methylmalonic acidemia and SLC25A13 gene c.852_855del for citrin deficiency." (PMID 33514801, 2021). "Phenylketonuria (PKU) is an autosomal recessive metabolic disease caused by mutations in the gene encoding phenylalanine hydroxylase (PAH)." (PMID 33564846, 2021). "In another study, an AAVHSC15 editing vector was used to edit the PAH gene on chromosome 12, mutations of which result in phenylketonuria." (PMID 35098210, 2021). "In classical phenylketonuria (PKU) phenylalanine (Phe) accumulates due to functional impairment of the enzyme phenylalanine hydroxylase caused by pathogenic variants in the PAH gene." (PMID 34412683, 2021). "A phenylalanine hydroxylase–deficient pig model of phenylketonuria is established and characterized." (PMID 33055427, 2020). "Phenylketonuria (PKU) stems from phenylalanine hydroxylase enzyme deficiency where the essential amino acid phenylalanine (Phe) is not converted into tyrosine." (PMID 32256622, 2020). "Phenylalanine hydroxylase–deficient (PAH-deficient) phenylketonuria (PKU) results in systemic hyperphenylalaninemia, leading to neurotoxicity with severe developmental disabilities." (PMID 33055427, 2020). "Phenylketonuria (PKU) is an autosomal recessive disorder caused by a deficiency of phenylalanine hydroxylase (PAH), which converts the amino acid phenylalanine into tyrosine." (PMID 32181140, 2020). "Mutations in the phenylalanine hydroxylase gene (PAH) lead to phenylketonuria (PKU) which, depending on the seriousness of the mutations, can be mild (Phe levels 300–600 μM), moderate (Phe levels 600–1200 μM), or severe (Phe levels >1200 μM)." (PMID 32260076, 2020). "Classical phenylketonuria is caused by gene mutations on the 12th chromosome, which encodes phenylalanine hydroxylase (PAH)." (PMID 32283743, 2020). "Phenylketonuria is an autosomal recessive disorder caused by a deficiency in the key enzyme PAH, which is necessary for the conversion of the amino acid phenylalanine to tyrosine." (PMID 31471952, 2020). "Phenylketonuria is a genetic disorder affecting the metabolism of phenylalanine (phe) due to a deficiency in the enzyme phenylalanine hydroxylase." (PMID 32107425, 2020). "First, SNP rs5030858 causes a missense mutation (R408W) in PAH, which encodes the phenylalanine hydroxylase responsible for converting phenylalanine to tyrosine, and the mutation is known to cause phenylketonuria." (PMID 30640898, 2019). "Phenylketonuria (PKU) is a recessive disorder of phenylalanine metabolism due to mutations in the gene for phenylalanine hydroxylase (PAH)." (PMID 31551819, 2019). "Phenylketonuria is a hereditary metabolic disorder due to the deficiency of tetrahydrobiopterin or phenylalanine hydroxylase." (PMID 31636599, 2019). "Phenylketonuria (PKU) is an inherited deficiency in the enzyme phenylalanine hydroxylase (PAH), which, when poorly-managed, is associated with clinical features including deficient growth, microcephaly, seizures, and intellectual impairment." (PMID 31331350, 2019). "Deficiency of phenylalanine hydroxylase causes phenylketonuria (PKU) with elevated phenylalanine (Phe) levels and associated neuropsychiatric and neurocognitive symptoms." (PMID 29973227, 2018). "Classic phenylketonuria is a result of near complete or complete deficiency of phenylalanine hydroxylase activity which will lead to profound and irreversible intellectual disability in the absence of dietary restriction of phenylalanine." (PMID 29850564, 2018). "Screen-printed gold electrode (SPGE) with thiolated DNA probes was used to detect the point mutation of the phenylalanine hydroxylase (PAH) enzyme, which is the cause of Phenylketonuria." (PMID 29899282, 2018). "In this work, we sought out to study the pathogenicity of two novel intronic PAH variants identified in phenylketonuria patients." (PMID 29684050, 2018).